RNU6-1320P (RNA, U6 small nuclear 1320, pseudogene)
Gene: Small nuclear RNA gene on chromosome 2 (94,846,533 to 94,846,639, reverse strand). Ensembl gene ENSG00000212140.
Homologues: Orthologues: chimpanzee U6 (100% identical), macaque U6 (93% identical), macaque U6 (92% identical), dog U6 (70% identical), mouse Gm54642 (61% identical), mouse Gm22279 (60% identical), rat LOC120101210 (58% identical). Paralogues in human: RNU6-1193P (99% identical), RNU6-1269P (99% identical), RNU6-368P (99% identical), RNU6-538P (99% identical), RNU6-599P (98% identical), U6 (96% identical), U6 (95% identical), RNU6-316P (94% identical), RNU6-55P (94% identical), U6 (94% identical), RNU6-954P (93% identical), RNU6-821P (86% identical), and 1288 more.